MSI1 (musashi RNA binding protein 1)
Diseases named in the same sentence as MSI1 in open-access papers (continued):
Sharing a sentence is not in itself a finding about the gene and the disease.
lung carcinoma (12 papers, 2013 to 2025). "In lung cancer, MSI1 is a diagnostic marker and is highly expressed in spheroid cultures of tumor cells." (PMID 32448364, 2020). "In this study, we investigated the potential of the stem cell and progenitor cell marker, Musashi1 (Msi1), as a diagnostic marker and potential therapeutic target for lung cancer." (PMID 23715514, 2013). "In the present study, we evaluated the role of Msi1 in the proliferation of lung cancer cells and its utility as a diagnostic marker for lung cancers of varying histological subtypes." (PMID 23715514, 2013). "The association between Msi1 expression in less differentiated lung cancer cells and proliferation also suggests that it may serve as a readily accessible marker of progression or response to therapy if it is present in sputum and bronchial washings from lung cancer patients." (PMID 23715514, 2013). "Thus, Msi1 is a sensitive and specific diagnostic marker for all lung cancer subtypes." (PMID 23715514, 2013). "Msi1 is well expressed in lung cancer cells and, particularly, at the level of tumorspheres isolated from lung cancer cell lines." (PMID 30060526, 2018). "Studies on tumorspheres isolated from lung cancer cell lines suggest that Musashi 1 (Msi1) is a potential marker of lung CDSCs." (PMID 30060526, 2018). "Analyses of lung cancers indicated that Msi1 protein or RNA expression can serve as a highly sensitive diagnostic marker for lung cancer irrespective of the histological subtype." (PMID 23715514, 2013). "In the present study, we report that Msi1 KD in A549 and H520 lung cancer cells inhibited the proliferation of the stem-like spheroid tumor cells that was associated with inhibition of Notch and Wnt signaling." (PMID 23715514, 2013). "Msi1 expression was evaluated by western blotting in 14 lung cancer cell lines and one immortalized airway epithelial cell line." (PMID 23715514, 2013). "Msi1 expression was enriched in A549 and H520 lung cancer cells under cell culture conditions that promoted the formation of less differentiated spheroid colonies shown to be enriched for stem-like cells." (PMID 23715514, 2013). "Msi1 was expressed in 12/14 lung cancer cell lines, with high levels in about half of them, as well as in the epithelial cell line." (PMID 23715514, 2013). "Analyses of lung cancers indicated that Msi1 protein or RNA expression served as a highly sensitive diagnostic marker in >80% of >300 lung cancers irrespective of histological subtype." (PMID 23715514, 2013). "The majority of primary lung cancer biopsies exhibited varying patterns of Msi1 expression as previously noted in lung cancer specimens." (PMID 23715514, 2013). "Moreover, MSI1 modulates malignancy and chemoresistance of lung cancer cells via activating the Akt signaling." (PMID 32448364, 2020). "Indeed, silencing of MSI1 inhibits Wnt and Notch pathways and decreases spheroid colony formation in lung cancer." (PMID 32448364, 2020). "In primary lung cancer, Msi1 protein expression was elevated in 86% of 202 tissue microarray specimens, and Msi1 mRNA was increased in 80% of 118 bronchoscopic biopsies, including metastatic disease, but was rarely detected in adjacent normal lung tissue and in non-malignant diseased tissue." (PMID 23715514, 2013). "This is in line with findings in lung cancer implicating MSI2 in DNA damage repair and in triple-negative breast cancer regarding double knockdown of MSI1 and MSI2." (PMID 40843174, 2025). "This supports the pivotal role of MSI1 in promoting and sustaining GBM-CSC properties, also reported in other malignancies, e.g., breast and lung cancer." (PMID 33291443, 2020). "Since CD133 has been widely used as a lung cancer ‘stem cell’ marker, monolayer and spheroid cultures of A549 and H520 cells were sorted for CD133 and Msi1 mRNA levels determined." (PMID 23715514, 2013). "Msi1 expression was also assessed by qRT-PCR in 102 lung cancers and 16 non-malignant lung tissues collected by bronchoscopic biopsy." (PMID 23715514, 2013).
lung carcinoma (continued). "Lung cancer analyzed by tissue microarray or bronchoscopic biopsy expressed Msi1 protein or RNA in ≥80% of tumor specimens regardless of histological subtype." (PMID 23715514, 2013). "Similar to the tissue microarray findings, 80% of lung cancers were Msi1+, irrespective of age, gender, histology, degree of differentiation or stage of disease, but was detectable in only 2 of 16 non-malignant specimens." (PMID 23715514, 2013). "Lung tumors expressed Msi1 in a focal, scattered or diffuse pattern in 86% of 202 lung cancer specimens irrespective of age, gender, histology and stage of disease." (PMID 23715514, 2013).
cervical carcinoma (11 papers, 2008 to 2025). A carcinoma arising from either the exocervical squamous epithelium or the endocervical glandular epithelium. "Overexpression of Msi1 impaired the expression of BAK, and inhibiting Msi1 expression increased its expression in cervical cancer cells." (PMID 33758618, 2021). "In this study, we found that the expression of Msi1 inhibited cervical cancer cell apoptosis in vitro and in vivo." (PMID 33758618, 2021). "Consistently, in our study, cervical cancer cells exhibited resistance to apoptosis in response to exogenous expression of Msi1 both in vitro and in vivo." (PMID 33758618, 2021). "To examine the prognostic value of CSCs markers in cervical cancer, we evaluated the correlation between Msi1, ALDH1, Sox2 and CD49f expression and prognosis in CSCC patients." (PMID 26499463, 2015). "To investigate the potential roles of CSC markers in the development of cervical cancer, we determined the expression of Msi1, ALDH1, Sox2 and CD49f in 179 paraffin-embedded cervical carcinoma samples by immunohistochemistry." (PMID 26499463, 2015). "All of these results indicated that the Msi1 protein enhanced the tumor formation of cervical cancer cells in vivo." (PMID 25362645, 2014). "The relative expression level of Msi1 in these cervical cancer samples was higher than that in the normal cervical tissues (P<0.05)." (PMID 25362645, 2014). "The cell cycle analysis showed that Msi1 over-expression accelerated the transition of cervical cancer cells from the G0/G1 phase to the S phase, whereas Msi1 down-regulation blocked the transition of cervical cancer cells from the G0/G1 phase to the S phase." (PMID 25362645, 2014). "All of these results indicated that Msi1 was a positive pivotal regulator of the cell cycle in cervical cancer cells." (PMID 25362645, 2014). "Msi1 was found by immunocytochemistry and Western blot analysis to be expressed in all four cervical cancer cell lines (SiHa, HeLa, C33A and Caski)." (PMID 25362645, 2014). "In this study, we found Msi1 was highly expressed in cervical cancer tissues, and over-expressing Msi1 in cervical cancer cells enhanced tumor formation and cell proliferation and accelerated cells into the S phase." (PMID 25362645, 2014). "In this study, we examined the expression of Nanog, NS and Msi1 in cervical epithelial lesions of varying severity and in cervical carcinomas by immunohistochemical analysis and assessed their association with various prognostic variables." (PMID 18419830, 2008). "In CIN II-III and cervical carcinoma tissues, Nanog, NS and Msi1 were moderately or strongly expressed, in contrast to low expression levels in normal cervical epithelia and CIN I cells." (PMID 18419830, 2008). "However, the mechanisms by which Msi1 affects the survival of cervical cancer cells, such as apoptosis, are still unclear." (PMID 33758618, 2021). "In addition, rescue the expression of BAK in Msi1 expressing cervical cancer cells induced the increase of apoptosis cells." (PMID 33758618, 2021).
cervical carcinoma (continued). "Notably, the expression of mTOR was increased in Msi1-overexpressing cells but decreased in siMsi1-modified cells, suggesting another possible mechanism by which Msi1 promotes the proliferation of cervical cancer cells." (PMID 33758618, 2021). "Therefore, our in vitro and in vivo experiments support the fact that Msi1 is a tumor enhancer for cervical carcinoma." (PMID 25362645, 2014). "All of these data indicated that Msi1 expression could promote the proliferation of cervical cancer cells in vitro." (PMID 25362645, 2014). "Whereas, down-regulating Msi1 by shRNA in cervical cancer cells inhibited tumor formation and cell proliferation and slowed cell into the S phase, suggesting that Msi1 might act as cell cycle regulator." (PMID 25362645, 2014). "All of these results indicated that Msi1 was up-regulated in cervical carcinoma." (PMID 25362645, 2014). "The role of Msi1 in cervical cancer is unknown, and the molecular mechanisms of cervical carcinoma are not fully understood." (PMID 25362645, 2014). "Our findings indicate that Nanog, NS and Msi1 may be involved in carcinogenesis of the cervix and progression of cervical carcinoma." (PMID 18419830, 2008). "In addition, Msi1 increased the expression of mTOR, suggesting that Msi1 accelerated the proliferation of cervical cancer cells might not only through regulating the cell cycle, but also modulating the AKT signaling." (PMID 33758618, 2021). "However, the effect of Msi1 on apoptosis in cervical cancer is still unclear." (PMID 33758618, 2021). "Therefore, the effect of Msi1 on cervical cancer cell apoptosis should be explored in vivo and in vitro, which might provide a strategy to repress the expression of Msi1 for the treatment of cervical cancer." (PMID 33758618, 2021). "Our study suggested that Msi1 might be an target in the molecular therapy for cervical carcinoma." (PMID 25362645, 2014). "Msi1 might be an important protein in controlling the progression of cervical carcinoma." (PMID 25362645, 2014). "High expression of Msi1, ALDH1, and Sox2, and low expression of CD49f predict poor prognosis for cervical cancer patients receiving postoperative chemotherapy." (PMID 26499463, 2015). "The aims of this work were therefore to evaluate the expression pattern of Msi1, ALDH1, Sox2, and CD49f in cervical cancer tissues and to determine their significance in predicting the prognosis in cervical cancer patients." (PMID 26499463, 2015). "Another indirect role of MSI1 was established in modulating Wnt signaling, where silencing MSI1 led to the downregulation of EMT markers and inhibition of Wnt pathway activities in cervical cancer." (PMID 41516083, 2025).
cervical carcinoma (continued). "It has been reported that Msi1 could promote the EMT, invasion and metastasis of cervical cancer cells by activating the Wnt signaling pathway." (PMID 33758618, 2021). "Although Msi1 expression has been discovered in various carcinomas, its role in cervical cancer is not well defined." (PMID 25362645, 2014). "The roles of Nanog, NS and Msi1 in development and progression of cervical carcinoma have, until now, not been well documented." (PMID 18419830, 2008). "In our study, Msi1 was found to be up-regulated from normal cervix, cervical carcinoma in situ, to invasive cervical carcinoma and different cervical cancer cell lines, but there no different Msi1 expression levels according to clinical pathological parameters such as age and pathological stage." (PMID 25362645, 2014). "However, there were no positive correlations among Nanog, NS and Msi1 expression levels and the clinical pathological prognostic factors analyzed, indicating that overexpression of these three stem-cell-abundant proteins in cervical epithlium is not related to the prognosis of cervical carcinoma." (PMID 18419830, 2008). "Furthermore, the analysis of cervical cancer samples and normal cervix samples data from GEPIA (gepia.cancer-pku.cn) also present a negative correlation between Msi1 and BAK (r=-0.19, P=0.0009)." (PMID 33758618, 2021).
brain tumor (9 papers, 2006 to 2023). "High levels of Msi1 have been reported in several malignancies including brain tumors thereby associating Msi1 and cancer." (PMID 18826648, 2008). "Msi1 and miR-137 have apparently antagonistic roles and opposite expression patterns in neurogenesis and brain tumor formation." (PMID 24465609, 2014). "The decrease in the MSI1 protein level in brain tumor cells led to a reduction in the transplanted tumor mass in the host mouse brain and a repression of cell proliferation." (PMID 22428049, 2012). "Taken together, these results indicate that MSI1 is involved in cell-cycle control, especially at the M-phase, in brain tumor cells." (PMID 22428049, 2012).
gastric cancer (9 papers, 2012 to 2022). A primary or metastatic malignant neoplasm involving the stomach. "A recent study has shown that MSI1 was overexpressed in gastric cancer cell lines and gastric cancer tissues." (PMID 32448364, 2020). "We chose a set of genes that were reported to encode gastric cancer stem cell markers such as LGR5, CD133, CD44, CD54, ABCG2 and MSI1, and then performed qPCR to detect their expression in both NANOGP8-transfected (SGC7901-NANOGP8) and mock cells (SGC7901-NC)." (PMID 29689047, 2018). "MiR-1278 targets MSI1 to inhibit gastric cancer development." (PMID 34691176, 2021). "As a result, MSI1 was regulated directly by miR-330 in gastric cancer cells." (PMID 32448364, 2020). "While, other studies found miR-330-3p was lowly expressed in gastric cancer cell lines and tissues, and over-expression of miR-330-3p could inhibit gastric cancer progression through targeting MSI1." (PMID 29311822, 2017). "Moreover, miR-330-3p functions as a tumor suppresser in gastric cancer by targeting RRRX1 and MSI1." (PMID 36568518, 2022).
endometriosis (7 papers, 2010 to 2024). The growth of functional endometrial tissue in anatomic sites outside the uterine body. "The present study underlines the potential role of MSI-1 and MSI-2 as therapeutic targets in endometriosis." (PMID 35269992, 2022). "As these data suggest a potential mechanistic involvement of Musashi proteins in endometriosis, the aim of this study is to elucidate the effect of MSI-1 and MSI-2 knockdown on endometriosis development in vitro." (PMID 35269992, 2022). "Specifically, the expression of MSI-1, MSI-2, of the transcription factor HES-2 and the cell cycle regulator p21 are significantly reduced in patients with endometriosis according to the data." (PMID 35269992, 2022).
hepatocellular carcinoma (7 papers, 2008 to 2025). A malignant tumor that arises from hepatocytes. "It is already evidenced that overexpression of MSI1 triggers activation of the Wnt/β-catenin signaling pathway, thereby increasing migration and invasion of hepatocellular carcinoma cells." (PMID 32448364, 2020). "On the other hand, stemness properties of cancer stem cells in hepatocellular carcinoma are dependent to MSI1 and CD44 expression." (PMID 32448364, 2020). "In conclusion, our study revealed that both MSI1 and MSI2 are abnormally expressed in hepatocellular carcinoma, but only the abnormal expression of MSI2 was associated with poor prognosis in a large series of hepatocellular carcinoma." (PMID 24305552, 2014). "MSI1 was also found to positively correlate with Wnt activation in hepatocellular carcinoma (HCC), and this correlation was shown in patients with poor prognosis." (PMID 41516083, 2025). "In hepatocellular carcinoma cells, LEF1-AS1 can modulate the miR-10a-5p level to upregulate MSI1 (Musashi1) expression and activate AKT signaling, contributing to chemoresistance." (PMID 41511293, 2025).
ovarian carcinoma (7 papers, 2015 to 2024). A malignant neoplasm originating from the surface ovarian epithelium. "A link between MSI1 and drug resistance was shown in ovarian cancer–derived in which a MSI1 depletion abolished the paclitaxel resistance of A2780–derived paclitaxel resistant cells." (PMID 34062997, 2021). "It has been previously verified that Musashi1 (MSI1) is a target of miR-761 in ovarian cancer." (PMID 39136001, 2024). "Then, ovarian cancer cells were subjected to siRNA-based dual knockdown of MSI-1 and MSI-2." (PMID 34768932, 2021). "While chemosensitization has been described for both MSI-1 knockdown and MSI-2 targeting independently in ovarian cancer cells, radiation effects have not previously been investigated." (PMID 34768932, 2021).
liver cancer (5 papers, 2010 to 2024). An epithelial or non-epithelial malignant neoplasm that arises from the liver. "To test whether MSI1 and PCBP2 overexpression was sufficient to activate rod-specific exons, we transfected these proteins into HepG2 cells, a liver cancer cell line used by the ENCODE project." (PMID 31919425, 2020). "After robust overexpression of MSI1 or PCBP2 (with or without simultaneous PTBP1 knockdown) in liver cancer cell lines, Ling and colleagues observed that MSI1 expression combined with downregulation of PTBP1 is linked to the activation of photoreceptor-specific exons." (PMID 38438733, 2024). "We find that PTBP1 knockdown and MSI1 and PCBP2 overexpression are sufficient to activate many photoreceptor-specific exons in HepG2 liver cancer cells." (PMID 31919425, 2020).